TREM1 (triggering receptor expressed on myeloid cells 1)
Diseases named in the same sentence as TREM1 in open-access papers (continued):
Sharing a sentence is not in itself a finding about the gene and the disease.
viral hepatitis (4 papers, 2016 to 2021). An acute or chronic inflammation of the liver parenchyma caused by viruses. "Taken together, our findings indicate that TREM1 influences the course of and the immunopathology associated with viral hepatitis, mainly through the activity of neutrophils." (PMID 27328755, 2016). "To investigate the role of TREM1 in viral hepatitis, we assessed 1) the plasma levels of sTREM1 in human hepatitis virus infection and in murine LCMV infection, and 2) the effect of TREM1 deficiency on murine LCMV hepatitis in Trem1−/− mice." (PMID 27328755, 2016). "To investigate the functional role of TREM1 in viral hepatitis, we infected wild type C57BL/6 mice or Trem1−/− mice with LCMV-WE at a dose of 106 FFU." (PMID 27328755, 2016). "Instead, we found that TREM1 expression during viral hepatitis was essentially confined to liver-infiltrating neutrophils, which also seemed to be the major source of shed sTREM1." (PMID 27328755, 2016). "As these findings seemed to confirm that TREM1 might play a role in viral hepatitis, we used Trem1−/− mice to study the possible function of TREM1 in viral liver infection." (PMID 27328755, 2016). "In mice, experimental viral hepatitis induced by infection with Lymphocytic Choriomeningitis Virus (LCMV)-WE was likewise associated with increased sTREM1 in serum and urine, and with increased TREM1 and its associated adapter molecule DAP12 in the liver." (PMID 27328755, 2016). "Thus, TREM1 seemed to aggravate the immunopathology of viral hepatitis, mainly by increasing the inflammatory activity of neutrophils." (PMID 27328755, 2016). "However, we find here that the increased immunopathology in wild-type mice, as compared to Trem1−/− mice, was rather associated with protracted viral hepatitis and not accelerated clearance." (PMID 27328755, 2016). "Thus, the fact that both Trem2−/− and Trem1−/− mice show a protective phenotype in viral hepatitis indicates distinct cell type-specific and non-redundant roles of these TREM family members in liver pathology." (PMID 28900132, 2017). "Thus, TREM1 may be an attractive target to reduce the immunopathology of viral hepatitis without affecting, or even accelerating viral clearance." (PMID 27328755, 2016).
endometritis (3 papers, 2019 to 2022). An acute or chronic, usually bacterial infectious process affecting the endometrium. "TREM1 deficiency has been reported to inhibit LPS-induced inflammatory response in an endometritis model with a highly pathogenic LPS infection in mice uteri." (PMID 35100093, 2022). "Recently, a study has reported a positive association between TREM1 and LPS-induced inflammatory response in mouse model of endometritis." (PMID 35100093, 2022). "The results of the present study suggest the potential of TREM‐1 deficiency for the treatment of E. coli‐infected endometritis." (PMID 31365951, 2019). "Our results illustrate an anticipated pathogenic impact of TREM‐1 on endometritis during LPS infection and indicate that blocking of TREM‐1 in LPS‐induced endometritis holds considerable promise for blunting excessive inflammation." (PMID 31365951, 2019). "More importantly, a recent study has reported that knocking out TREM1 may have the ability to inhibit lipopolysaccharide (LPS)-induced inflammatory response in an endometritis model with a highly pathogenic LPS infection in mice uteri." (PMID 35100093, 2022). "TREM‐1 deficiency attenuates endometritis induced by lipopolysaccharide in mice." (PMID 34750987, 2021). "In summary, the present study provided strong evidence of the protective effects of TREM‐1 deficiency against LPS‐induced endometritis in mice, the mechanism of which could be deduced as knocking out of the Trem‐1 inhibited the LPS‐induced production of IL‐1β, IL‐6 and TNF‐α." (PMID 31365951, 2019). "Based on previous studies, this study further elucidated the mechanism of TREM1 in LPS-stimulated HEnEpCs and demonstrated the therapeutic potential of targeting TREM1 in the treatment of endometritis." (PMID 35100093, 2022). "Collectively, USF2 promotes endometritis by upregulating TREM1, thereby activating TLR2/4-NF-κB pathway." (PMID 35100093, 2022). "Triggering receptor expressed on myeloid cells 1 (TREM1) participates in the development of endometritis." (PMID 35100093, 2022). "In the current study, an LPS‐induced endometritis mouse model was created to determine whether Trem‐1 knockout affected the inflammatory responses of the uterus." (PMID 31365951, 2019). "We thus hypothesized that USF2 might transcriptionally regulate TREM1 expression in endometritis." (PMID 35100093, 2022). "In the present study, an in vitro model of LPS-induced human endometrial epithelial cells (HEnEpCs) was established to investigate whether USF2 can induce transcriptional activation of TREM1 and promote endometritis by regulating TLR2/4-NF-κB signaling pathway." (PMID 35100093, 2022). "Therefore, we presumed that USF2 might transcriptionally activate TREM1 to promote endometritis." (PMID 35100093, 2022). "This study aims at identifying the effects and interaction of TREM1 and upstream stimulatory factor 2 (USF2) in endometritis by using a model of lipopolysaccharide (LPS)-induced human endometrial epithelial cells (HEnEpCs)." (PMID 35100093, 2022).
gout (3 papers, 2019 to 2026). A condition characterized by painful swelling of the joints, which is caused by deposition of urate crystals. "In this study, we found that the levels of TREM-1 and sTREM-1 were increased in patients with gouty arthritis." (PMID 31885496, 2019). "Together, our findings suggest that blocking TREM-1 may prove beneficial as a novel strategy in the treatment of gout as well as other inflammasome-mediated diseases." (PMID 41582609, 2026). "Several studies showed that TREM-1 was increased in gout patients and animal models." (PMID 31885496, 2019). "Our results indicated that TREM-1 and sTREM-1 may play an important pathological role in gouty arthritis." (PMID 31885496, 2019). "The purpose of this study was to investigate the potential role of TREM-1 in THP-1 cells and peripheral blood mononuclear cells (PBMCs) from patients with gouty arthritis (GA)." (PMID 31885496, 2019).
Granuloma (3 papers, 2016 to 2020). A compact, organized collection of mature mononuclear phagocytes, which may be but is not necessarily accompanied by accessory features such as necrosis. "TREM-1-positive cells were also found in granulomas and multinuclear giant cells, although the expression was weaker than that observed in the alveolar airspaces." (PMID 29844416, 2018). "The low expression of TREM-1 may also have an impact, via the amount and spectra of proinflammatory cytokines production, to the granuloma formation leading to poorly defined small granulomas in HP compared with sarcoidosis." (PMID 32508528, 2020). "Interestingly, we found that the expression of TREM-1 was stronger in alveolar macrophages than in the macrophages from granulomas." (PMID 29844416, 2018). "Recent studies demonstrate the role of TREM receptors in the T cell immune response, the involvement of TREM-1 in the activation of systemic inflammation, and the role of TREM-2 in granuloma formation." (PMID 32508528, 2020).
Hypertension (3 papers, 2017 to 2022). The presence of chronic increased pressure in the systemic arterial system. "Moreover, TREM-1 (that mediates inflammatory cardiac injury), CINC2 (CXCL-3) that is induced by IL-1 (and also called macrophage inflammatory protein 2 beta, MIP-2β), and fibroblast growth factor binding protein (FGF-BP) (that is implicated in hypertension) were also suppressed in ZO-C heart." (PMID 28408970, 2017).
intracerebral hemorrhage (3 papers, 2024 to 2025). A cerebrovascular disorder characterized by bleeding into one or both cerebral hemispheres including the basal ganglia and the cerebral cortex. "Significant increase in serum TREM-1 levels after intracerebral hemorrhage (ICH) suggests its association with the inflammatory response, hemorrhage severity, and long-term functional prognosis." (PMID 39062850, 2024). "Experiments in which mouse TREM-1 was ubiquitously ablated showed that these mice were protected against intracerebral hemorrhage-induced neurobehavioral deficits, indicating that triggering of TREM-1 on myeloid cells induces a neuroinflammatory response." (PMID 39809747, 2025).
leukemia (3 papers, 2020 to 2025). A malignant (clonal) hematologic disorder, involving hematopoietic stem cells and characterized by the presence of primitive or atypical myeloid or lymphoid cells in the bone marrow and the blood. "TREM1 has also been reported to cooperate with diminished DNA damage response in vivo to promote expansion and leukemic progression in Fanca-/- pre-leukemia stem cells." (PMID 32765489, 2020). "Importantly TREM1 ablation in preleukemic stem cells compromised proliferation and delayed leukemia in vivo." (PMID 40677705, 2025).
liver diseases (3 papers, 2019 to 2022). "TREM1 expression in resident and infiltrating immune system cells promotes inflammation during the course of liver disease." (PMID 36119721, 2022). "TREM1 and TREM2 participate in inflammation, metabolism, fibrosis, and tumorigenesis—all of which are closely associated with liver diseases." (PMID 33297569, 2020). "Additional studies have also reported that endogenous ligands for TREM1, HMGB1 and HSP70, are also upregulated in various liver diseases and may further drive hepatic inflammation through TREM1." (PMID 31260499, 2019). "Here, we review the function of TREM1 and TREM2 in different liver diseases based on inflammation, providing a more comprehensive perspective for the treatment of liver-related diseases." (PMID 33297569, 2020).
migraine (3 papers, 2024 to 2025). "We used male C57BL/6 mice to establish a model of migraine, and the effect of TREM1 in female animal models needs to be further studied." (PMID 38177990, 2024). "Our data demonstrated that the inhibition of TREM1 could exhibit a partial efficacy in mitigating pain hypersensitivity in migraine mice, while exhibiting no discernible impact on normal mice." (PMID 38177990, 2024).
oral squamous cell carcinoma (3 papers, 2024 to 2025). "In oral squamous cell carcinoma (OSCC), CD46 shows markedly high expression with diffuse strong positivity on tumor cell membranes/cytoplasm, TREM1 is overexpressed, and LC3B/ATG5 expression is low." (PMID 41415031, 2025).
parasitic infection (3 papers, 2014 to 2021). "Using PbANKA-infected ICR mice to investigate the involvement of TREM-1 during malaria infection, and found that mice with low parasitemia levels have low concentrations of plasma TREM-1 and vice versa." (PMID 34899708, 2021). "In a TREM-1 knock-out mouse model of viral or parasitic infection, it was demonstrated that the lack of TREM-1 signaling mitigated the severity of inflammation and disease (as compared to the wild-type mice) without, however, affecting pathogen clearance." (PMID 31581596, 2019).
schizophrenia (3 papers, 2013 to 2023). A major psychotic disorder characterized by abnormalities in the perception or expression of reality. "This comparison revealed that GP6 signaling, a pathway implicated in schizophrenia, and TREM1 signaling, which is related to inflammation and glial activation, are uniquely activated in aged motor neurons." (PMID 37154159, 2023). "The cellular and molecular module for immune system involving IL-2 pathway and TREM-1/DAP12 pathway were proposed for potential susceptibility for schizophrenia." (PMID 24564241, 2013). "Strong correlations with immune system pathways were found which involve the IL-2 and TREM-1/DAP12 pathway which are responsible for the etiology mechanism for schizophrenia in PID." (PMID 24564241, 2013). "For example, the over-expressing schizophrenia candidate genes, SIRPB1, SYK and LCK, are responsible for signal transduction in cytokine production; immune responses involving IL-2 and TREM-1/DAP12 pathways are relevant for the etiology mechanism of schizophrenia." (PMID 24564241, 2013).
type 1 diabetes mellitus (3 papers, 2011 to 2020). A chronic condition characterized by minimal or absent production of insulin by the pancreas. "These included IL-6 signaling, IL-10 signaling, TREM1 signaling, MIF regulation of innate immunity, type I diabetes mellitus signaling, p38 MAPK signaling, toll-like receptor signaling, and acute phase response signaling." (PMID 21777429, 2011). "The pathways related to the Th1 response (HMGB1 Signaling, Neuroinflammation Signaling pathway, TREM1 Signaling, MIF-mediated Glucocorticoid Regulation, Dendritic Cell Maturation, and Type I Diabetes Mellitus Signaling) were activated at 6, 12 and 24 h after M. avium infection." (PMID 33520738, 2020). "Additionally, the most significant canonical pathways were IL-6 signaling, IL-10 signaling, TREM1 signaling, MIF regulation of innate immunity, type I diabetes mellitus signaling, p38 MAPK signaling, toll-like receptor signaling, and acute phase response signaling." (PMID 21777429, 2011).
abdominal aortic aneurysm (2 papers, 2025). Enlargement and ballooning of the vessel that supplies arterial blood to the abdomen, pelvis and legs. "Previous studies have shown that therapeutic inhibition of TREM-1 can blunt excessive inflammatory cell infiltration, resulting in a decreased severity of liver injury and abdominal aortic aneurysm." (PMID 39809747, 2025). "It competes with TREM-1 for ligand binding, reducing aortic inflammation during abdominal aortic aneurysm." (PMID 41226426, 2025).
acute lung injury (2 papers, 2021). A condition of lung damage that is characterized by bilateral pulmonary infiltrates (pulmonary edema) rich in neutrophils, and in the absence of clinical heart failure. "A second study implicated both NLRP3 inflammasome activation and the immune response amplifier triggering receptor expressed on myeloid cells 1 (TREM-1) in modulating LPS-induced acute lung injury." (PMID 34639062, 2021).
atrial fibrillation (2 papers, 2025 to 2026). A disorder characterized by an electrocardiographic finding of a supraventricular arrhythmia characterized by the replacement of consistent P waves by rapid oscillations or fibrillatory waves that vary in size, shape and timing and are accompanied by an irregular ventricular response. "In models where atrial fibrillation is induced by Ang II, inhibition of TREM-1 markedly reduces macrophage infiltration, diminishes NLRP3 activation, and suppresses the overall inflammatory response, ultimately ameliorating electrical remodeling in the atria." (PMID 41561130, 2025).
autoimmune disorders (2 papers, 2019 to 2021). "In contrast to microglia, macrophages express TREM-1 rather than TREM-2, and although this isoform plays a role in inflammatory responses, the functions of TREM-1 still need to be further studied in a CNS autoimmunity context." (PMID 30967783, 2019).
bacterial meningitis (2 papers, 2009 to 2024). Inflammation of the membranes surrounding the brain and spinal cord due to a bacterial infection. "Triggering receptor expressed on myeloid cells 1 (TREM-1) activation, through danger- and pathogen-associated molecular patterns (DAMPs and PAMPs), has been associated with cytokine production in bacterial meningitis." (PMID 39469711, 2024).
brain edema (2 papers, 2023 to 2025). Increased intracellular or extracellular fluid in brain tissue. "Collectively, these results demonstrate that TREM-1 inhibition through LP17 treatment effectively mitigates TBI-induced cerebral edema and BBB disruption, improves CBF restoration, and promotes recovery of BBB associated proteins." (PMID 40761800, 2025). "To assess the therapeutic efficacy of TREM-1 inhibition on cerebral edema, we employed the wet/dry weight method." (PMID 40761800, 2025). "Furthermore, inhibition of TREM‐1 with LP17 could improve neurobehaviour outcomes and brain edema." (PMID 37170484, 2023).
brain tumor (2 papers, 2020 to 2022). "Moreover, HMGB1 released from brain tumor necrotic cells or produced by tumor-associated macrophages can recruit TREM-1+ monocytes into the tumor." (PMID 32684831, 2020). "Moreover, we expect that HMGB1 released from brain tumor necrotic cells or produced by tumor-associated macrophages can recruit TREM-1+ monocytes into the tumor." (PMID 32684831, 2020).
breast tumor (2 papers, 2021). "In this report, we present first evidence that high TREM1 expression in breast tumors is associated with inferior clinical outcomes of patients." (PMID 34956864, 2021). "This work demonstrates, for the first time, that TREM1 expression in breast tumors associates with a reduced interval to clinical metastasis and a decreased responsiveness to neoadjuvant chemotherapy." (PMID 34956864, 2021). "Immunohistochemical analysis of breast tumor tissues confirmed the co-localization of TREM1 protein expression with the pan-macrophage marker CD68." (PMID 33575478, 2021). "Our findings fit a model where myeloid-derived TREM-1 signaling is operative in human breast tumors and antagonizes anti-tumor immune processes." (PMID 34956864, 2021). "Here, we investigated the prognostic impact and immunological correlates of TREM1 expression in breast tumors." (PMID 34956864, 2021). "To more precisely characterize TREM1 expression in the breast tumor microenvironment, we profiled 770 cells from a fresh surgical TNBC specimen by single-cell (sc) RNAseq." (PMID 34956864, 2021). "Side-by-side analyses were conducted for the set of all breast tumors, and for the basal-like breast tumors, alone, since they showed the highest average expression of TREM-1 as compared to other subtypes in the MC1 and MC2 cohorts." (PMID 34956864, 2021). "In parallel, we investigated TREM-1 expression directly by immunofluorescence staining using a breast tumor tissue microarray consisting of >40 invasive ductal and lobular carcinomas positive or negative for the clinical markers ER, PGR and HER-2." (PMID 34956864, 2021). "Our findings raise the possibility that the targeting of TREM-1 signaling in breast tumors may represent a viable immunotherapeutic strategy." (PMID 34956864, 2021). "Similarly, we observed that high TREM1 expression associated with inferior DMFS, and that this association was most prominent in breast tumors that otherwise exhibited a survival advantage in the context of high CD8+ T cell infiltration (as estimated by CIBERSORT)." (PMID 34956864, 2021). "By analyzing single-cell sequencing datasets, we further characterized cellular aspects of TREM1 expression in breast tumors and identified TREM1 transcriptional correlates indicative of myeloid TREM-1 activation in the breast TME and candidate mechanisms of pro-tumorigenic growth." (PMID 34956864, 2021). "In our analysis of the TCGA breast tumor cohort, we observed significant positive correlations between TREM1 expression and the expression of TREM-1 target cytokines (IL1B, IL8, IL6 and CCL2) and markers of MDSCs and TAMs (CD11B/ITGAM, OLR1, CD14 and CD206/MRC1)." (PMID 34956864, 2021).
cardiac hypertrophy (2 papers, 2021 to 2022). "Treg from lymphoid tissues, LN and spleen, shared six pathways including Th2 pathway, cardiac hypertrophy signaling, TREM1 signaling, nitric oxide and reactive oxygen species, thrombin signaling and endothelin signaling." (PMID 34084175, 2021).
cerebral infarction (2 papers, 2022 to 2024). An ischemic condition of the brain, producing a persistent focal neurological deficit in the area of distribution of the cerebral arteries. "Researchers have used genetic and pharmacological approaches to inhibit TREM-1 expression and found reduced brain infarct size and increased survival in mice." (PMID 36273145, 2022). "Research indicates that TREM1 may play a key role in the inflammatory response following cerebral infarction and could potentially serve as a biomarker for monitoring therapeutic outcomes and disease progression." (PMID 38672048, 2024).